PF4 (platelet factor 4)
Diseases named in the same sentence as PF4 in open-access papers (continued):
Sharing a sentence is not in itself a finding about the gene and the disease.
Thrombocytopenia (continued). "While high levels of anti‐PF4 paraprotein (4–18 g/L) have been reported in patients with monoclonal gammopathy of thrombotic significance, all of these patients had chronic presentations, with only mild thrombocytopenia and no preceding viral infections." (PMID 40298004, 2025). "Spontaneous heparin-induced thrombocytopenia (S-HIT) is an even less frequent variant of HIT, with only a handful of reports available in the literature, where unexplained thrombocytopenia and/or thrombosis without recent heparin exposure occurs in the setting of positive anti-PF4 antibodies." (PMID 40126221, 2025). "Anti-PF4 autoantibodies have been detected in a vaccine-induced catastrophic thrombotic thrombocytopenia (VITT) disorder in vaccination for SARS-CoV-2, and this disorder presents as extensive thrombosis in atypical sites, primarily in the cerebral venous, alongside thrombocytopenia." (PMID 41226302, 2025). "The clinical resemblance of unexplainable thrombocytopenia and thrombosis to spontaneous heparin-induced thrombocytopenia (spHIT) prompted investigators to test patient serum for antibodies against platelet factor 4 (PF4/CXCL4), a protein extensively studied for its role in the pathogenesis of HIT." (PMID 38398325, 2024). "In addition to thrombocytopenia, these patients had elevated D-dimer, often decreased fibrinogen, and high levels of anti-PF4 antibodies that activated platelets independent of heparin." (PMID 36448024, 2023). "Thrombocytopenia occurred in one person with negative anti-PF4/polyanionic antibodies." (PMID 37674185, 2023). "According to one study, five patients infected by venous thrombosis and thrombocytopenia 7–10 days after injecting the first AstraZeneca dose of adenoviral vector vaccine showed significant levels of antibodies to platelet factor 4-poly-anion complexes, without any prior heparin exposure." (PMID 35582622, 2022). "Unlike classical heparin-induced thrombocytopenia, endogenous polyanions, such as chondroitin sulfate or polyphosphate, may trigger PF4 antibody formation in autoimmune heparin-induced thrombocytopenia." (PMID 35632556, 2022). "Platelet degranulation itself could also be affected, as PF4 levels in type 2B patients without thrombocytopenia were also lower than in type 1 VWD." (PMID 36165954, 2022). "KKO (Anti–human PF4 monoclonal antibodies to PF4; KKO causes thrombocytopenia in an in vivo model of HIT) and RTO (Anti–human PF4 monoclonal antibodies to PF4, RTO does not cause thrombocytopenia in an in vivo model of HIT) have been characterized, including their amino acid sequences." (PMID 34526009, 2021). "A high prevalence of PF4/heparin antibodies has been reported in cardiosurgical and orthopedic patients, as well as in volunteer blood donors without a clinical syndrome of thrombosis/thrombocytopenia." (PMID 34358129, 2021). "One limitation of the present paper is that we have not tested the PF4 antibody titer immediately after plasma exchange, and hence we do not know whether the recurrent thrombocytopenia was due to a persistent high level of PF4 antibody titer." (PMID 34341358, 2021). "All patients had high levels of antibodies relative to platelet factor 4 (PF4)–polyanion complexes without previous exposure to heparin, pointing to a rare vaccine-related variant of spontaneous heparin-induced thrombocytopenia referred to as vaccine-induced immune thrombotic thrombocytopenia." (PMID 34639132, 2021). "SMFS provided an initial hypothesis that ‘not only heparin but also a subset of anti-PF4/Heparin antibodies induced thrombocytopenia in patients without heparin exposure’." (PMID 29614814, 2018). "State-of-the-art diagnostic criteria for spontaneous HIT have been proposed and include thrombocytopenia and thrombosis without previous heparin exposure along with detectable anti-PF4/heparin antibodies with platelet-activating potential in the absence of heparin." (PMID 28698883, 2017).
Thrombocytopenia (continued). "To evaluate the property of oligonucleotides to bind and form antigenic complexes with PF4, we used a monoclonal antibody (KKO) that has similar properties to the naturally occurring anti-PF4/heparin antibodies found in patients with heparin-induced thrombocytopenia/thrombosis." (PMID 29107969, 2017). "Previous studies revealed that lower PF4 expression was not due to thrombocytopenia." (PMID 25317080, 2014). "Finally, we demonstrated that the patients who tested negative for the anti-PF4/heparin antibody and who also exhibited a thrombocytopenia or underwent administration of antiplatelet drugs were at significantly increased risk for clinical bleeding." (PMID 23646121, 2013). "In order to determine whether the reduced serum PF4 expression was associated with reduced platelet in MDS patients and benzene-exposed workers, studies revealed that lower PF4 expression was not due to thrombocytopenia." (PMID 23915341, 2013). "However, in contrast to patients with HIT, none of the patients that developed thrombosis and thrombocytopenia post-vaccination were known to have been treated with heparin, and the anti-PF4 IgG Abs in their sera could bind PF4 in the absence of heparin." (PMID 34557868, 2021). "Furthermore, they do not always activate platelets in presence of heparin/PF4 complexes, although they do so in presence of PF4 alone, suggesting that they were induced by another mechanism than classical heparin-induced thrombocytopenia." (PMID 34029337, 2021). "Despite negative anti-PF4 antibodies, which excluded HIT, thrombocytopenia necessitated the temporary suspension of anticoagulation." (PMID 40755701, 2025). "Immunoglobulin G antibodies against PF4-polyanion complexes were elevated in all patients, indicating VITT rather than heparin-induced thrombocytopenia." (PMID 36851087, 2023). "Evidence for the independence of immune responses to PF4 and the SARS-CoV-2 spike protein lie in the lack of increase in anti-PF4 antibodies and potential subsequent thrombocytopenia or thrombosis in former VITT patients who contracted COVID-19 later." (PMID 37834770, 2023). "VITT resembles HIT in that it is associated with platelet-activating antibodies against platelet factor 4 (PF4), however patients with VITT develop thrombocytopaenia and thrombosis without exposure to heparin." (PMID 34613452, 2021). "It follows that the reduction of serum PF4 and CTAP-III contents in ND ALL are not due to thrombocytopenia and hypoleucocytosis." (PMID 25317080, 2014). "We determined and compared serum PF4 content between newly diagnosed AML with and without thrombocytopenia." (PMID 23915341, 2013).
COVID-19 (150 papers, 2020 to 2026). A disease caused by infection with severe acute respiratory syndrome coronavirus 2. "While our investigation focused on the interaction between PF4 and the original SP of COVID-19, it is importance to consider variant-specific interactions for a comprehensive understanding." (PMID 38540666, 2024). "Pathogenic platelet factor 4 (PF4) antibodies contributed to the abnormal coagulation profiles in COVID-19 and vaccinated patients." (PMID 38540666, 2024). "Our results allowed us to propose a mechanism for the development of PF4/SP antibodies caused by the response of immune cells to the formed PF4/SP complexes in COVID-19 and VITT patients." (PMID 38540666, 2024). "Platelet activation is a major driver of inflammation/thrombogenesis, and von Willebrand factor (vWF) and Platelet Factor 4 (PF4) are deeply involved in the pathogenesis of COVID-19-associated coagulopathy." (PMID 37189799, 2023). "Elevated levels of PF4 have been linked to enhanced platelet activation and to a hypercoagulable state associated with increased D-dimer levels in sepsis and COVID-19." (PMID 36980378, 2023). "Many of these mediators, including PF4, bind to heparin, and it is likely that their excessive release is a major cause of heparin resistance observed patients suffering from severe COVID-19." (PMID 35163743, 2022). "This raises the important question of what does induce anti-CL antibodies in COVID-19-associated coagulopathies and the answer, as was also the case with anti-PF4 antibodies, is most likely bacteria." (PMID 36232795, 2022). "Anti-platelet factor 4 immunoglobulins were also investigated as autoantibodies associated with COVID-19 vaccination." (PMID 35911726, 2022). "Mon HLA and Mon CD14 inside Delta samples differ in expression for the cytokine panel (CCL3, VEGFA, CCL5, CCL4, CXCR4, IL7R, CXCL8, and PF4) that have been found associated with COVID-19 severity and mortality." (PMID 36230912, 2022). "The presence of anti-PF4 associated with HIT suggests an alternate anticoagulant treatment to heparin should be used for COVID-19 patients or that patients are screened for auto-Ab prior to treatment." (PMID 34930107, 2021). "The adenoviral vector-based AstraZeneca and Janssen COVID-19 vaccines have been associated with rare cases of thrombosis, believed to be triggered, among other factors, by vector binding to the blood protein platelet factor 4 (PF4)." (PMID 41509905, 2026). "Furthermore, vaccine-induced thrombotic thrombocytopenia (VITT) has been confirmed due to the development of platelet-activating PF4-antibodies or HIT-like antibodies after COVID-19 vaccination, causing severe thrombotic thrombocytopenia." (PMID 38540666, 2024). "Bacteria associated with severe COVID-19 are good candidates, since they express CL in their cell membranes, and cross-reactivity between some of these bacterial antibodies and both β2GPI and PF4 has been demonstrated experimentally." (PMID 36769320, 2023). "Beyond its hemostatic activity, PF4 is responsible for neutrophil recruitment to sites of inflammation/infection and strongly induces the formation of NETs, which are central mediators of COVID-19-associated coagulopathy." (PMID 35874830, 2022). "Circulating immune complexes can directly activate platelets by initiating complement binding, have been observed as a cause of platelet activation in COVID-19-related contexts, often contain PF4-reactive IgG (and thus bacteria-induced antibodies), and participate in the formation of NETosis." (PMID 36232795, 2022). "In addition, a previous study found a positive correlation between serum reactivity and PF4 in vaccine-induced immune thrombotic thrombocytopenia patients with COVID-19, suggesting a possible causal relationship." (PMID 36499742, 2022).
COVID-19 (continued). "Reports have emerged that some of the vaccines against COVID-19 may be associated with vaccine-induced immune thrombotic thrombocytopenia (VITT) which is triggered by the presence of antibodies that recognize platelet factor (PF4) bound to platelets." (PMID 37046448, 2023). "Large-scale human adenoviral COVID-19 vaccinations appear to be associated with rare cases of vaccine-induced immune thrombocytopenia (VITT) that may be due to the interaction of the viral vector with platelet factor 4 (PF4)." (PMID 35746597, 2022). "We observe that two months after the acute infection, patients still display dysregulated gene expression related to vascular, platelet and coagulation pathways, including PF4 (platelet factor 4), which may explain the prolonged thrombotic risk following COVID-19." (PMID 36522333, 2022). "In the present study, we identified Ad types that lack binding to PF4 and show that ChAdY25 and Ad26 vectors with capsids equivalent to the COVID-19 vaccines bind to PF4." (PMID 41509905, 2026). "We aimed to investigate the involvement of anti-PF4/H antibodies during COVID-19 and after vaccination, particularly in patients with systemic inflammatory disease (SID)." (PMID 40123654, 2025). "In the cohort of 182 controlsHCW, we measured IgG anti-PF4/H levels in sera at baseline and after COVID-19 vaccination." (PMID 40123654, 2025). "This case illustrates the risk of fatal vaccine-induced immune thrombotic thrombocytopenia after an AstraZeneca COVID-19 vaccination and emphasizes the need for early recognition and specialized testing, including PF4 ELISA, to improve patient outcomes." (PMID 41427155, 2025). "In the present study, we found that the prevalence of positive anti-PF4/H after COVID-19 vaccination was also low in controls (0.0%-4.8%) and patients with SID (1.7%-2.0%)." (PMID 40123654, 2025). "This study was designed to investigate the relevance of anti-PF4/H antibody detection according to platelet activation in COVID-19 and after COVID-19 vaccination in the general population and in patients with SIDs." (PMID 40123654, 2025). "This adenovirus vector COVID-19 vaccine complication has been named VITT and is caused by anti-PF4 immunoglobulin G (IgG) mainly heparin-independent." (PMID 40123654, 2025). "Then, baseline and post COVID-19 vaccination IgG anti-PF4/H levels were measured in 24 sera from controls2021." (PMID 40123654, 2025). "Vaccine-induced thrombotic thrombocytopenia (VITT) has also been described in healthy individuals following COVID-19 vaccination and it is attributed to platelet factor 4 (PF4) antibody-mediated platelet and complement activation." (PMID 38761322, 2024). "A significant negative correlation was found between serum 25(OH)D and anti-PF4 levels in mild COVID-19 patients (P = .035; R = −0.236)." (PMID 39287233, 2024). "Conversely, VITT generally presents 4 to 42 days following the primary dose of adenoviral vector-based COVID-19 vaccine, with anti-PF4 specific antibodies directed against the heparin-binding site." (PMID 38398325, 2024). "The aim of this study is to analyze the correlation between serum 25-hydroxy-cholecalciferol [25(OH)D] levels and anti-PF4 antibodies among COVID-19 patients." (PMID 39287233, 2024). "This methodology leverages the antigen complex formation between COVID-19 vaccine and the PF4, a process meticulously observed by dSTORM." (PMID 38910248, 2024). "The strength of our study is the fact that it is the first study to provide evidence of a significant correlation between serum 25(OH)D levels and anti-PF4 in mild COVID-19 patients." (PMID 39287233, 2024). "As multiple complex factors including PF4/virus and PF4/soluble-SP can develop in COVID-19 patients, a high concentration of PF4-antibodies can be developed." (PMID 38540666, 2024).
COVID-19 (continued). "Background/Objectives: Adenoviral vector-based vaccines against COVID-19 rarely cause vaccine-induced immune thrombocytopenia and thrombosis (VITT), a severe adverse reaction caused by IgG antibodies against platelet factor 4 (PF4)." (PMID 39852782, 2024). "Elevated levels of soluble markers of platelet activation (P selectin, PF4), increased platelet aggregates, and platelet-derived microparticles suggest the activation of platelets circulating in the bloodstream of COVID-19 patients." (PMID 39795908, 2024). "This research aims to analyze the correlation between serum 25(OH)D and anti-PF4 antibodies in COVID-19 patients." (PMID 39287233, 2024). "This explains how the body generates platelet-activating anti-PF4 antibodies in COVID-19 patients, as detected recently." (PMID 38540666, 2024). "Fibrin thrombi and platelet factor 4 (PF4)-positive thrombi were found in close proximity to TF-expressing areas in COVID-19 ARDS lungs and correlated with TF expression." (PMID 39457048, 2024). "Based on our results, we proposed a mechanism for the generation of PF4 antibodies in COVID-19 patients." (PMID 38540666, 2024). "This means that COVID-19 patients with heparin therapy also suffer from HIT in which platelet-activating anti-PF4/H antibodies are generated." (PMID 38540666, 2024). "They found that, for COVID-19 patients, PF4 and serotonin levels were significantly higher in plasma than platelets compared to the healthy subjects, indicating platelets were activated in COVID-19 patients and released more granules than healthy people." (PMID 37762435, 2023). "Here, we characterized the cellular origin of PS-exposing EVs in plasma from COVID-19 patients as well as their association with inflammation- and coagulation-related parameters, including CRP, HMGB-1, PF4, and TF." (PMID 38069209, 2023). "Sustained platelet activation in COVID-19 boosts the release of PF4 and HMGB-1, inducing neutrophil activation and the release of NETs, which strongly promote coagulation." (PMID 38069209, 2023). "ADAMTS-13 levels were reduced, with marked inter-individual variation, and the vWf:ADAMTS-13 ratio was increased in convalescent COVID-19 cases, while levels of platelet factor 4 (PF4), a putative protector of vWf, were also elevated in the same population." (PMID 37175942, 2023). "This immune-mediated condition is caused by the development of pathological anti-platelet factor 4 (PF4) antibodies following vaccination against COVID-19, which leads to intense activation of platelets and the coagulation system." (PMID 37854872, 2023). "Albeit only a small percentage of EVs was associated with PF4 (COVID-19, 3.0 [3.0–4.0] %; healthy controls, 2.0 [0.5–3.0] %), PF4+ EVs were significantly elevated in COVID-19 patients compared to healthy donors (7525 [3878–16,385] vs. 1050 [170–2280] EVs/μL)." (PMID 38069209, 2023). "The lung autopsies of COVID-19 patients showed upregulated platelet expression of PF4 (CXCL4), which promotes blood coagulation and activates the NF-κB signaling pathway in ECs, acting as a potential agent of both thrombosis and inflammation." (PMID 36979908, 2023). "It has been reported that COVID-19 patients with severe disease had higher levels of anti-platelet factor 4 (PF4) antibodies than patients with milder disease or healthy controls." (PMID 37620330, 2023). "We explored correlations between PF4 autoantibody levels at T3 and specific covariates, including vaccine type, age, sex, COVID-19 status, study site, and days between vaccination and venous blood sampling." (PMID 38140254, 2023). "The COVID-19 vaccines interact with the platelets or the platelet factor 4 (PF4) and this interaction results in vaccine-induced immune thrombotic thrombocytopenia (VITT)." (PMID 36366386, 2022). "The same PF4-mediated serious complications have also occurred with another adenoviral vector-based vaccine, which is COVID-19 Vaccine Janssen by Johnson & Johnson." (PMID 35456110, 2022).